SENP1 (SUMO specific peptidase 1)
Description:
Protease that catalyzes two essential functions in the SUMO pathway. The first is the hydrolysis of an alpha-linked peptide bond at the C-terminal end of the small ubiquitin-like modifier (SUMO) propeptides, SUMO1, SUMO2 and SUMO3 leading to the mature form of the proteins. The second is the deconjugation of SUMO1, SUMO2 and SUMO3 from targeted proteins, by cleaving an epsilon-linked peptide bond between the C-terminal glycine of the mature SUMO and the lysine epsilon-amino group of the target protein. Deconjugates SUMO1 from HIPK2. Deconjugates SUMO1 from HDAC1 and BHLHE40/DEC1, which decreases its transcriptional repression activity. Deconjugates SUMO1 from CLOCK, which decreases its transcriptional activation activity. Deconjugates SUMO2 from MTA1. Inhibits N(6)-methyladenosine (m6A) RNA methylation by mediating SUMO1 deconjugation from METTL3 and ALKBH5: METTL3 inhibits the m6A RNA methyltransferase activity, while ALKBH5 desumoylation promotes m6A demethylation. Desumoylates CCAR2 which decreases its interaction with SIRT1. Deconjugates SUMO1 from GPS2.
Synonyms: SuPr-2
Tractability: Small molecule: a high-quality ligand is known; it has a binding pocket of medium quality. PROTAC: ubiquitination databases record sites on it; its protein half-life has been measured; a small molecule that binds it is known.
Target class: Protease; Enzyme; Cysteine protease CE clan; Cysteine protease C48 family; Cysteine protease
Gene: Protein-coding gene on chromosome 12 (48,039,784 to 48,106,308, reverse strand). Ensembl gene ENSG00000079387.
Subcellular location: Nucleus; Cytoplasm
Subcellular location (Human Protein Atlas): Nucleoplasm; Focal adhesion sites
Pathways (Reactome):
Metabolism of proteins: SUMO is proteolytically processed
Signal Transduction: RHOF GTPase cycle
Gene Ontology:
Molecular function: protein binding; SUMO-specific endopeptidase activity; deSUMOylase activity; endopeptidase activity; cysteine-type peptidase activity
Biological process: positive regulation of transcription by RNA polymerase II; protein desumoylation; regulation of mRNA stability; protein sumoylation; proteolysis; regulation of postsynapse assembly
Cellular component: cytoplasm; nucleoplasm; nucleus; glutamatergic synapse; postsynaptic cytosol; presynaptic cytosol
Genetic constraint (gnomAD): Loss-of-function variants: 14 observed, 51.36 expected, observed/expected ratio (o/e) 0.27, 90% interval 0.18 to 0.43. The upper end of that interval is the gene's LOEUF score, 0.43, which puts it in group 1 of 6, group 1 being the genes least tolerant of losing a copy. Missense variants: 397 observed, 524.67 expected, observed/expected ratio (o/e) 0.76, 90% interval 0.7 to 0.82. Synonymous variants: 182 observed, 187.63 expected, observed/expected ratio (o/e) 0.97, 90% interval 0.86 to 1.1.
Homologues: Orthologues: chimpanzee SENP1 (99% identical), macaque SENP1 (99% identical), pig SENP1 (94% identical), dog SENP1 (93% identical), guinea pig SENP1 (90% identical), rabbit SENP1 (90% identical), rat Senp1 (88% identical), mouse Senp1 (88% identical), tropical clawed frog senp1 (55% identical), zebrafish senp1 (46% identical). Paralogues in human: SENP2 (30% identical), SENP5 (20% identical), SENP3 (18% identical).
Diseases named in the same sentence as SENP1 in open-access papers:
SENP1 is named in the same sentence as 126 diseases in open-access papers, as found by Europe PMC text mining. Sharing a sentence is not in itself a finding about the gene and the disease. The quoted sentences say what the papers report.
prostate carcinoma (39 papers, 2013 to 2026). A carcinoma that arises from epithelial cells of the prostate gland. "For instance, in vitro downregulation of miR-145 has been associated with increased SENP1 expression levels in prostate cancer tissue samples, while enhanced expression of miR-145 has been proven to result in cell cycle arrest by blocking SENP1." (PMID 40002226, 2025). "The positive expression of SENP1 in prostate cancer patients is significantly associated with poor survival." (PMID 38389923, 2024). "Another research also implicated that SENP1 contributed to tumor metabolism in prostate cancer cells." (PMID 38389923, 2024). "SENP1 is linked to prostate cancer progression because SENP1 regulation of matrix metallopeptidase 2 (MMP2) and matrix metallopeptidase 9 (MMP9) through the hypoxia-inducible factor 1-alpha (HIF-1α) signaling pathway promotes progression." (PMID 35408841, 2022). "For example, a low expression of miR-145 is correlated with high expression of SENP1 in prostate cancer cells, and introduction of miR-145 causes cell cycle arrest via inhibition of SENP1." (PMID 34503213, 2021). "The SUMO protease SENP1 was identified as a factor that promotes the removal of C-terminal SUMO moieties from human HDAC1 in a prostate cancer model, causing upregulation of the androgen receptor." (PMID 34003109, 2021). "Overall, our study demonstrates that SENP1 overexpression is frequent in ERG positive prostate cancer and linked to PTEN deletions." (PMID 26202067, 2015). "Certain studies have shown that SENP1 is associated with the development of prostate cancer and that SENP1 overexpression is found in thyroid oncocytic tumors." (PMID 23467634, 2013). "In addition to breast cancer, SENP1 overexpression has also been implicated in the development of bladder cancer, prostate cancer, neuroblastoma, osteosarcoma, and lung cancer." (PMID 37468105, 2023). "Mechanistically, SENP1 overexpression was associated with the increased expression of several transcription factors essential for the development and progression of prostate cancer, such as androgen receptor (AR) and HIF-1α, which is critical for neoangiogenesis." (PMID 33923236, 2021). "Hence, SENP1 inhibitors could serve as effective therapy for more aggressive PTEN-deficient prostate cancer." (PMID 27852060, 2017). "Upregulation of SENP1 was recently reported in various cancer types, including breast cancer, lung cancer, prostate cancer, HCC, and colorectal cancer." (PMID 41438340, 2026). "In prostate cancer PC-3 cells, Mc contributed to an increase in SENP1 accumulation proportionally to the Mc concentration." (PMID 41303693, 2025). "By inhibiting SENP1 activity, Mc contributes to the reduction in prostate cancer cell proliferation." (PMID 41303693, 2025). "TPL down-regulated SENP1 expression on both mRNA and protein levels in dose-dependent and time-dependent manners, resulting in an enhanced cellular sumoylation in prostate cancer cells." (PMID 41303693, 2025). "In prostate cancer, Triptolide decreases SENP1 mRNA and protein levels in both dose-dependent and time-dependent manner, resulting in cellular SUMOylation level increasing." (PMID 38389923, 2024). "Another research also detected the overexpression of SENP1 in prostate intraepithelial neoplasia lesions and prostate cancer tissues from patients." (PMID 38389923, 2024). "The deSUMOylation of HK2 mediated by SENP1 desensitizes chemotherapy response in prostate cancer cells with docetaxel treatment." (PMID 38389923, 2024). "In prostate cancer, SENP1 silence enhances E-cadherin expression while inhibits vimentin expression." (PMID 38389923, 2024). "In prostate cancer, SENP1 is overexpressed in prostatic intraepithelial neoplasia and prostate cancer lesion compared to normal prostate epithelia." (PMID 38389923, 2024). "Overexpressed SENP1 promotes androgen receptor-dependent cell proliferation in prostate cancer cells." (PMID 38389923, 2024).
prostate carcinoma (continued). "SENP1 has been investigated in many cancers including prostate cancer, breast cancer, and colon cancer, which played important roles in suppressing cell proliferation and invasion." (PMID 36979893, 2023). "An elevated level of SENP1 in prostate cancer cells has a significant impact on androgen-mediated cell growth, promoting the development and progression of prostate cancer." (PMID 38203649, 2023). "Recent studies demonstrate that SENP1 enhances the stemness of certain tumor cells, such as certain hepatocellular carcinoma and prostate cancer cell lines." (PMID 36284084, 2022). "In tumors such as prostate cancer, neuroblastoma (NB), and breast cancer, SENP1 is also related to tumor development and metastasis 21,35,36." (PMID 35342335, 2022). "SENP1 overexpression has been previously reported to enhance tumor growth by desumoylating components of signaling pathways relevant to breast or prostate cancers." (PMID 36284084, 2022). "For example, sumoylation of AR suppresses its transcriptional activity, and overexpression of SENP1 in prostate cancer enhances AR transcriptional activity, promoting cancer progression and metastasis." (PMID 36284084, 2022). "The Yeh group demonstrated that overexpression of SENP1 was present in more than 60% of samples of prostate cancer and prostatic intraepithelial neoplasia lesions." (PMID 33923236, 2021). "As a member of the de-SUMOylation protease family, SUMO-specific protease 1 (SENP1) is elevated in prostate cancer (PCa) cells and is involved in PCa pathogenesis." (PMID 33603816, 2021). "Triplotide and momordin Ic (Mc) are natural SENP1 inhibitors that have shown anticancer activity towards prostate cancer." (PMID 34503213, 2021). "Inhibition of SENP1 expression in high-grade metastatic prostate cancer cells can affect the bone remodeling ability of HIF-1α and its downstream matrix metalloproteinase (MMP)-2 and MMP-9, and then inhibit the bone metastasis of prostate cancer cells." (PMID 33791211, 2021). "In agreement with these cell experiments, the histopathological analysis showed that in prostate cancer patient samples, upregulation of both HK2 and SENP1 is associated with poor prognosis and poor response to docetaxel-based chemotherapy." (PMID 33753739, 2021). "In a subsequent study, these authors identified SENP1 as upregulated in human prostate cancers and found that overexpression of SENP1 was sufficient to drive prostate neoplasia in a mouse model." (PMID 34003109, 2021). "CDX2 inhibits the expression of miR-145-5p, thereby relieving the inhibitory effect of miR-145-5p on the translation of SENP1 and affecting the invasion and migration of prostate cancer cells." (PMID 33659248, 2021). "This introduces SENP1 in the progression of prostate cancer and suggests SENP1 as a prognostic marker and a therapeutic target for prostate cancer metastasis patients." (PMID 34276383, 2021). "miR-145-mediated down-regulation of SENP1 induced quiescence of prostate cancer cells and reversed SENP1-promoted tumorigenesis in mice, pointing to miR-145 as a molecule of therapeutic value against cancer." (PMID 33923236, 2021). "SENP1 also promotes EMT of prostate cancer cells via regulating SMAD4 de-SUMOylation and it regulates PTEN stability to promote prostate cancer development." (PMID 33572160, 2021). "Previous studies have shown that SENP1 is highly expressed in human prostate cancer specimens and is correlated with the expression of hypoxia-inducible factor 1α (HIF1α)." (PMID 33123273, 2020). "Among the seven SENP members, SENP1 is widely localized in the nuclei and has been reported to play fairly important role in lung cancer, prostate cancer, colon cancer." (PMID 31969492, 2020). "Previously, it has been clearly reported that SENP1 is overexpressed in several types of human cancer, including colon cancer, prostate cancer, and breast cancer." (PMID 31969492, 2020).
prostate carcinoma (continued). "In this study, we developed a lentiviral vector, PLKO.1-shSENP1, to silence SENP1 in prostate cancer cells with high metastatic characteristics (PC3M)." (PMID 28417919, 2017). "One such protease SENP1 has been widely investigated in many cancers including prostate cancer, breast cancer and colon cancer." (PMID 28417919, 2017). "It has been reported that SENP1 is up-regulated in prostate cancer patients, and promotes both androgen receptors (ARs)-dependent and ARs-independent cell proliferation." (PMID 28417919, 2017). "Multiple studies indicate that SENP1 induction directly correlates with prostate cancer severity and recurrence." (PMID 27852060, 2017). "To study the effects of SENP1 on the biological effects of prostate cancer cells, we constructed a lentiviral vector expressing short hairpin RNA targeting SENP1, PLKO.1-shSENP1, and a control vector, PLKO.1-shScramble." (PMID 28417919, 2017). "In conclusion, SENP1 deSUMOylated SMAD4 to promote EMT via up-regulating E-cadherin in prostate cancer cells." (PMID 28417919, 2017). "Up-regulation of SENP1 promotes deSUMOylation of SMAD4 in prostate cancer cells, which reduces the SMAD4 levels and impairs TGF-β/SMADs-mediated transcription activities." (PMID 28417919, 2017). "In low endogenous SENP1 expressing prostate cancer cells, LNCaP, Ad5/F11p.SENP1 infection produced SENP1 protein efficiently." (PMID 28417919, 2017). "SUMO-specific protease 1 (SENP1), a member of the de-SUMOylation protease family, is elevated in prostate cancer (PCa) cells and is involved in PCa pathogenesis." (PMID 27449295, 2016). "In this study, by screening a small library of natural compounds, we identified Mc as novel SENP1 inhibitor that inhibited proliferation of prostate cancer cells in vitro and in vivo." (PMID 27449295, 2016). "An elevated SENP1 level was observed in thyroid oncocytic adenocarcinoma, prostate cancer and pancreatic ductal adenocarcinoma (PDAC)." (PMID 27178176, 2016). "Latest studies demonstrated that low expression of miR-145 was correlated with high expression of SENP1 in prostate cancer cell line PC-3." (PMID 27178176, 2016). "Silencing SENP1 level in highly metastatic prostate cancer cells perturbs their ability to metastasize to the bone and initiates secondary tumors." (PMID 27178176, 2016). "In this study, we demonstrate that Mc, a natural triterpenoid, is a novel SENP1 inhibitor with anti-prostate cancer activity in vitro and in vivo." (PMID 27449295, 2016). "Assessment of tissue from human prostate cancer patients indicates elevated mRNA levels of SENP1 and the SUMO2/3 deconjugating enzyme, SENP3." (PMID 27178176, 2016). "Together, these results suggest that SENP1 is a novel target in the treatment of prostate cancer and demonstrate for the first time that Mc has anti-prostate cancer activity." (PMID 27449295, 2016). "SENP1 expression is elevated in prostate cancer specimens and correlates with prostate cancer aggressiveness and recurrence." (PMID 27449295, 2016). "Immunohistochemically detectable SENP1 expression was found in about 35 % of prostate cancers in our study." (PMID 26202067, 2015). "Another study reported the down-regulation of SENP1 expression at both mRNA and protein levels by the natural product triptolide and thereby enhancing sumoylation in prostate cancer cells." (PMID 25893082, 2015). "Given that prostate cancer is characterized by AR-driven SENP1 expression, it is possible that drugs targeting SENP1, possibly in combination with anti-androgenic therapy, will also be effective in prostate cancer." (PMID 26202067, 2015). "These promising findings prompted us to study the putative prognostic value of SENP1 expression measurement in a large cohort including more than 12,400 European prostate cancers that have been assembled in a tissue microarray (TMA) format." (PMID 26202067, 2015).
prostate carcinoma (continued). "Other evidences for the role of SENP1 in prostate cancer tumorigenesis include the increase in androgen receptor activity and c-Jun dependent transcription." (PMID 25893082, 2015). "In the current study we analyzed prevalence and prognostic impact of the de-SUMOylation enzyme SENP1 in prostate cancer." (PMID 26202067, 2015). "This frequency is lower than what has been observed in two earlier IHC studies, reporting positive SENP1 staining in 76.5 % of 115 and high SENP1 expression in 47 % of 117 analyzed prostate cancers from Asian patients." (PMID 26202067, 2015). "The high number of tumors in our TMA enabled us to profoundly evaluate SENP1 in the context of key genomic alterations of prostate cancer." (PMID 26202067, 2015). "SENP1 expression was analyzed by immunohistochemistry on a tissue microarray containing more than 12,400 prostate cancer specimens." (PMID 26202067, 2015). "Given the paramount impact of IHC protocols on the positivity rates in TMA studies we would not view our data as strong evidence in favor of possible ethnical differences in SENP1 expression in prostate cancers." (PMID 26202067, 2015). "SENP1 has been shown to be crucial in the development of prostate cancer by modulating the SUMOylation of the androgen receptor." (PMID 24926368, 2014). "It effectively inhibits SENP1 activity with an IC50 of 15.37 μM in prostate cancer cells." (PMID 41303693, 2025). "Additionally, microRNA-145 mediates proliferation arrest through suppressing SENP1 activity in prostate cancer." (PMID 38389923, 2024). "SENP1 directly contributes to the bone metastasis of prostate cancer cells." (PMID 38389923, 2024). "High level of SENP1 predicts poor prognosis in prostate cancer patients." (PMID 38389923, 2024). "Knockdown SENP1 significantly attenuates colony formation ability in prostate cancer." (PMID 38389923, 2024). "Consequently, SENP1 can regulate the development and metastasis of certain cancers, such as breast and prostate cancers." (PMID 36284084, 2022). "Additionally, SENP1 expression directly correlated with prostate cancer aggressiveness and recurrence." (PMID 33923236, 2021). "Prostate cancer cell growth could be induced, because HIF1α activation and stabilization by SENP1 results in promoted Cyclin D1 and VEGF levels, angiogenesis, and cell growth." (PMID 34276383, 2021). "Mainly, numerous studies have been focused on the role of SENP1 in prostate cancer development." (PMID 33923236, 2021). "In summary, high expression of both HK2 and SENP1 might predict poor outcomes in prostate cancer patients." (PMID 33753739, 2021). "Additionally to MMP9, SENP1 regulated the expression of MMP2 through the HIF-1α signaling pathway in prostate cancer." (PMID 33923236, 2021). "Moreover, we demonstrate an inverse relationship between SENP1-hexokinase 2 axis and chemotherapy response in prostate cancer samples." (PMID 33753739, 2021). "Momordin Ic as a novel SENP1 inhibitor could inhibit proliferation of prostate cancer cells in vitro and in vivo by inducing cell cycle arrest and apoptosis." (PMID 33603816, 2021). "Likewise, we also created an adenovirus vector, Ad5/F11p-SENP1 to over-express SENP1 in prostate cancer cells with low metastatic potential (LNCaP)." (PMID 28417919, 2017). "Taken together, these studies suggest that SENP1 silencing could inhibit the EMT of prostate cancer cells via up-regulating SMAD4 expression." (PMID 28417919, 2017). "SUMO protease SENP1 is elevated in multiple carcinomas including prostate cancer (PCa)." (PMID 27852060, 2017). "To test if SENP1 could deSUMOylate SMAD4 in prostate cancer cells, we analyzed SMAD4 expression in PC3M cells after infection with PLKO.1-shSENP1 or PLKO.1-shScramble." (PMID 28417919, 2017). "Therefore, we propose that SENP1 up-regulation in prostate cancer cells deSUMOylates SMAD4, which in turn regulates E-cadherin, induces EMT of tumor cells and promotes tumor metastasis." (PMID 28417919, 2017).